ZBP1 (Z-DNA binding protein 1)
Diseases named in the same sentence as ZBP1 in open-access papers (continued):
Sharing a sentence is not in itself a finding about the gene and the disease.
liver fibrosis (1 paper, 2023). "To further investigate the importance of ZBP1-mediated necroptosis in the progression of BA and BDL liver fibrosis, we next studied the relationship between ZBP1 expression and fibrosis marker expressions." (PMID 36859525, 2023). "Blockage of S1PR2/ZBP1/p-MLKL axis caused the decrease of necroptosis, and importantly, the attenuation of liver fibrosis." (PMID 36859525, 2023). "We next employed Zbp1 siRNA-GeRPs to further confirm the importance of ZBP1/p-MLKL-mediated necroptosis in liver fibrosis." (PMID 36859525, 2023). "Our study for the first time demonstrated the vital role of macrophage necroptosis mediated by ZBP1/p-MLKL to the pathology of BA liver fibrosis." (PMID 36859525, 2023). "ZBP1 expression was upregulated in BA livers and the abnormal increased expression of ZBP1 in BA livers was correlated with liver fibrosis and prognosis." (PMID 36859525, 2023). "Furthermore, this process was mediated by ZBP1/p-MLKL, and the upregulated expression of ZBP1 in BA livers was correlated with liver fibrosis and prognosis." (PMID 36859525, 2023). "Moreover, in consistent with BA livers, we also detected p-MLKL+ZBP1+ macrophages (F4/80+ cells) in BDL-induced mouse liver fibrosis." (PMID 36859525, 2023). "The increased mRNA expression of ZBP1 in BA livers is correlated with liver fibrosis and prognosis." (PMID 36859525, 2023). "In conclusion, GDCA/S1PR2/ZBP1/p-MLKL mediated macrophage necroptosis plays vital role in the pathogenesis of BA liver fibrosis, and targeting this process may represent a potential therapeutic strategy for BA." (PMID 36859525, 2023). "In BDL-induced liver fibrosis, selectively knocking down of macrophage S1pr2, Zbp1 or Mlkl blocked S1PR2/ZBP1/p-MLKL axis." (PMID 36859525, 2023). "Selective blockage of S1PR2/ZBP1/p-MLKL axis in macrophage attenuated necroptosis and liver fibrosis in BDL mice." (PMID 36859525, 2023). "The results of Masson staining showed the reduction of collagen deposition in Zbp1 siRNA-GeRP-treated injured livers, which was in accordance with the decreases of Acta2 (α-SMA, the marker of liver fibrosis), Col1a1 (Col I) and Col3a1 expressions in Zbp1 siRNA-GeRPs-injection groups." (PMID 36859525, 2023). "In conclusion, all these results showed that blockage of GDCA/S1PR2/ZBP1/p-MLKL axis-mediated necroptosis, which was an important player of cholestatic liver fibrosis, could be potential target of BA liver fibrosis." (PMID 36859525, 2023).
liver inflammation (1 paper, 2023). "In consistent with Zbp1 siRNA-GeRP treatment group, Mlkl siRNA-GeRP injection also alleviated BDL-induced liver inflammation, injury and fibrosis." (PMID 36859525, 2023).
lung adenocarcinoma (1 paper, 2024). A carcinoma that arises from the lung and is characterized by the presence of malignant glandular epithelial cells. "Furthermore, we conducted clinical validation based on pathological specimens from 21 patients with lung adenocarcinoma and found that cg09897064 methylation is associated with ZBP1 expression and macrophage polarization, representing a novel immune checkpoint." (PMID 38369516, 2024). "This study examines the mechanistic association between cg09897064 methylation on Z-DNA binding protein 1 (ZBP1) in lung adenocarcinoma." (PMID 38369516, 2024).
mastitis (1 paper, 2021). Inflammation of breast tissue during lactation or postpartum due to an obstructed duct or infection. "Thus, the protective function of ZBP1 against mastitis needs to be considered." (PMID 34827157, 2021). "Through GWAS enrichment analysis and Phe-WAS, key genes, DEG ZBP1 and DSG TEF, were verified, which can be regarded as promising targets for improving bovine S. aureus mastitis defense and public health." (PMID 34827157, 2021).
metabolic syndrome (1 paper, 2024). A cluster of metabolic risk factors for CARDIOVASCULAR DISEASES and TYPE 2 DIABETES MELLITUS. "Using in silico data analysis, we created an mRNA-miRNA panel (ZBP1, HSPA1B, MAPK3 & mir-5192) associated with pancreatic cell dysfunction and metabolic syndrome and involved in necroptosis-related TNF pathway." (PMID 38961451, 2024).
metastatic cancer (1 paper, 2025). A carcinoma which has spread from the original site of growth to another anatomic site. "In summary, our sono‐controllable Janus hydrogel platform integrates strategies of ROS modulation, ZBP1 regulation, and oxygen supplementation, offering a groundbreaking therapeutic approach for treating metastatic cancer and bone defects with clinically promising dual‐targeted effects." (PMID 40908585, 2025).
Miscarriage (1 paper, 2025). A pregnancy that ends at a stage in which the fetus is incapable of surviving on its own, defined as the spontaneous loss of a fetus before the 22th week of pregnancy. "Furthermore, increased m6A methylation on NLRP3 mRNA mediated by METTL3 can enhance the interaction between Z-DNA-binding protein 1 (ZBP1) and NLRP3 proteins, promoting trophoblast cell apoptosis and leading to miscarriage." (PMID 40001550, 2025).
myocardial infarction (1 paper, 2023). Gross necrosis of the myocardium, as a result of interruption of the blood supply to the area, as in coronary thrombosis. "mtDNA was proposed to amplify necroptotic signaling via ZBP1 and has since been suggested as a ZBP1 agonist in different cancer settings and myocardial infarction." (PMID 37450010, 2023).
nonalcoholic fatty liver disease (1 paper, 2025). "In nonalcoholic fatty liver disease (NAFLD), lipotoxicity triggers mtDNA release through the ER stress–mitochondrial dysfunction cascade, the activating the cGAS-STING pathway to upregulate ZBP1." (PMID 41583472, 2025).
Obesity (1 paper, 2022). Accumulation of substantial excess body fat. "The levels of IRF7-associated ISG-encoding transcripts, including IFI16, ZBP1 and TMEM173 (STING1), were increased in the adipose tissue of children with obesity, reflecting their elevated IRF7 levels." (PMID 36443525, 2022).
osteoarthritis (1 paper, 2024). A noninflammatory degenerative joint disease occurring chiefly in older persons, characterized by degeneration of the articular cartilage, hypertrophy of bone at the margins and changes in the synovial membrane. "Z-DNA binding protein 1 (ZBP1) is a nucleic acid sensor that is involved in multiple inflammatory diseases, but whether and how it contributes to osteoarthritis (OA) are unclear." (PMID 39026271, 2024).
ovarian tumors (1 paper, 2023). "Z-DNA binding protein 1 (ZBP1/DLM-1/DAI) is the only mammalian protein other than ADAR1 that contains the Zα domains and is first identified in ovarian tumors in mouse ascites." (PMID 37771585, 2023).
prediabetes (1 paper, 2022). "In the current pilot study, the expressions of ZBP1, DDX58, NFKB1 and CHUK were significantly higher in the T2DM group compared to either healthy control or pre-DM patients, which may give us new predictive markers for the development of T2DM in prediabetes patients." (PMID 36139069, 2022).
prostate carcinoma (1 paper, 2023). A carcinoma that arises from epithelial cells of the prostate gland. "Particularly, considering the importance of some molecules, we used PRAD tissue and BPH tissue from West China Hospital to identify expression patterns, and anti-ZBP1 IHC was performed using prostate cancer tumor tissue samples." (PMID 37547288, 2023).
pterygium (1 paper, 2024). A wedge-shaped fibrovascular lesion arising from the bulbar conjunctiva and extending to the cornea. "The following compatible patterns of some representative inflammatory genes between the two groups were observed: (i) The downregulation of ZBP1 in both pterygiums, known for its involvement in antiviral immunity, could be associated with cellular stress, including oxidative stress." (PMID 38732006, 2024).
respiratory infection (1 paper, 2022). "Specifically, ZBP1 interactions with NLRP3 and AIM2 inflammasomes are described in the context of the bacteria and viruses such as Francisella novicida and influenza virus, indicating the importance of ZBP1 in host–pathogen interactions during respiratory infection." (PMID 35626718, 2022).
retina degeneration (1 paper, 2022). "ZBP1 is implicated as an upstream regulator of necrotic cell death; therefore, we hypothesize that chronic activation of microglia could in turn enhance mtDNA damage in RPE cells causing chronic activation of ZBP1 and subsequent retina degeneration." (PMID 34953858, 2022).
schizophrenia (1 paper, 2024). A major psychotic disorder characterized by abnormalities in the perception or expression of reality. "In conclusion, in the present study we identify a miR-99b-5p-Zbp1 pathway in microglia as a novel mechanism that likely contributes to the pathogenesis of schizophrenia." (PMID 38528182, 2024). "Dysregulation of a novel miR-99b-5p-Zbp1 (Z-DNA binding protein 1) pathway in microglia induces inflammatory responses and schizophrenia-like phenotypes in mice." (PMID 38528182, 2024). "Our findings suggest that reduced miR-99b-5p levels in microglia contribute to the pathogenesis of schizophrenia via the regulation of Zbp1-controlled neuroinflammation." (PMID 38528182, 2024). "This study shows that miR-99b-5p regulates Z-DNA binding protein 1 (Zbp1) to control inflammatory responses in microglia and the development of schizophrenia-like symptoms in mice." (PMID 38528182, 2024). "Our findings indicate that a novel miR-99b-5p-Zbp1 pathway in microglia might contribute to the pathogenesis of schizophrenia." (PMID 38528182, 2024).
skin cutaneous melanoma (1 paper, 2022). "Conversely, high expression of PANoptosis genes was beneficial in skin cutaneous melanoma (SKCM), with ZBP1, NLRP1, CASP8 and GSDMD expression consistently having positive prognostic effects." (PMID 36329783, 2022).
small cell lung carcinoma (1 paper, 2025). Small cell lung cancer (SCLC) is a highly aggressive malignant neoplasm, accounting for 10-15% of lung cancer cases, characterized byrapid growth, and early metastasis. "These Z-RNAs activate the Z-form nucleic acid-sensor ZBP1, which triggers cell death in mouse embryonic fibroblasts and small cell lung cancer (SCLC) cells." (PMID 41046514, 2025).
Splenomegaly (1 paper, 2025). Abnormal increased size of the spleen. "This arsenic exposure induced splenomegaly and histological abnormalities in the spleen and lungs of WT mice but not ZBP1-deficient mice." (PMID 41135682, 2025).
systemic inflammatory response syndrome (1 paper, 2022). SIRS is a serious condition related to systemic inflammation, organ dysfunction, and organ failure. "ZBP1-deficient mice were significantly protected in the setting of systemic inflammatory response syndrome (SIRS) induced by TNF and IFN-γ." (PMID 36040212, 2022).
tauopathy (1 paper, 2026). Neurodegenerative disorders involving deposition of abnormal tau protein isoforms (tau proteins) in neurons and glial cells in the brain. "Moreover, we find that this rescue of tauopathy seen with ZBP1 ablation is associated with dampened activation of microglia and astrocytes." (PMID 41972681, 2026). "Here, we show that ZBP1 deletion provides protection against tau pathology and neuronal loss in the PS19 mouse model of tauopathy." (PMID 41972681, 2026).
triple-negative breast carcinoma (1 paper, 2024). An invasive breast carcinoma which is negative for expression of estrogen receptor (ER), progesterone receptor (PR), and human epidermal growth factor receptor 2 (HER2). "Notably, downregulation of ZBP1 in human triple-negative breast cancer is associated with increased genome instability, immune suppression and poor patient prognosis." (PMID 38200309, 2024).
type 2 diabetes (1 paper, 2015). "Specifically, IRF7 and NLRC5 are associated with type 2 diabetes, and SP110 and ZBP1 are associated with waist circumference and body fat distribution, respectively." (PMID 25868721, 2015).
ulcerative colitis (1 paper, 2026). An inflammatory bowel disease involving the mucosal surface of the large intestine and rectum. "By targeting TSPO, Emapunil exerts anti-UC effects through downregulation of ZBP1, thereby providing a novel mechanism and a potential therapeutic strategy for the clinical management of ulcerative colitis." (PMID 42273694, 2026).
viral pneumonia (1 paper, 2026). Inflammation of the lung parenchyma that is caused by a viral infection. "For instance, in viral pneumonia, PANoptosis can be triggered by the synergistic actions of TNF-α and IFN-γ or activated upon Z-DNA binding protein 1 (ZBP1) recognition of influenza A virus (IAV)." (PMID 41521316, 2026).
infection (113 papers, 2008 to 2026). The state of being infected such as from the introduction of a foreign agent such as serum, vaccine, antigenic substance or organism. "For example, IRF1 was identified as a transcriptional modulator of ZBP1 because the level of ZBP1 is diminished in cells with IRF1 deficiency during infection." (PMID 41304245, 2025). "Consistent with previous studies, hCoV‐OC43 infection‐induced cell death was almost abolished in ZBP1‐deficient Beas‐2B cells." (PMID 40810650, 2025). "This dissociation between viral RNA abundance and particle production suggests that ZBP1 deficiency impairs virion assembly during early in vivo infection." (PMID 40810650, 2025). "Following hCoV‐OC43 infection, cell death was nearly abolished in ZBP1‐deficient cells, further supporting the essential role of ZBP1 in driving β‐coronavirus‐induced cell death in human bronchial epithelial cells." (PMID 40810650, 2025). "We further showed that ZBP1 deficiency resulted in significantly higher morbidity and mortality following infection with WNV NY99 and WNV Eg101 strains in mice." (PMID 40416961, 2025). "It was reported that Zbp1 expression was upregulated in the lungs following infection with major SARS-CoV-2 variants and contributed to lung inflammation and immune cell infiltration." (PMID 40822581, 2025). "Cell death is closely interconnected to the host immune response during infection, and ZBP1 was previously linked to cell death measured by lactate dehydrogenase (LDH) release." (PMID 39850894, 2024). "In contrast to WT mice, which recovered 15-18 days after infection, lung bronchial epithelial cells in most Zbp1-/- mice continued to produce virus and cause lung impairment, leaving the mice dead 9-12 days after infection." (PMID 37771585, 2023). "Conversely, ZBP1-deficient mice infected via the intratracheal route, which causes more severe and acute disease, tolerate infection better and develop less immunopathology." (PMID 37450010, 2023). "We show that the loss of ZBP1 in primary murine astrocytes results in a significant increase in the release of PFUs following infection with a neuroinvasive clinical strain of HSV-1." (PMID 35549723, 2022). "ZBP1 acts as a cytoplasmic DNA receptor in many types of pathogenic infections, including Toxoplasma gondii infection, Fungi, and Yersinia pseudotuberculosis." (PMID 36615244, 2022). "This PCD pathway can be triggered by ZPB1 (Z-DNA-binding protein 1) that, similarly to pyroptosis, was linked to infection." (PMID 35326698, 2022). "Our studies indicate that ZBP1 plays a crucial role in triggering necroptosis in murine glia following infection with a strain of HSV-1 that contains mutations in the ICP6 RHIM domain (unpublished observations)." (PMID 33042875, 2020). "Deletion of ZBP1 resulted in significantly higher morbidity and mortality after infection with a pathogenic WNV NY99 strain in mice." (PMID 31572318, 2019). "In the present study, we showed that high virus titers in the serum of ZBP1−/− mice were associated with elevated levels of anti-viral cytokines and chemokines after subcutaneous infection with WNV." (PMID 31572318, 2019). "Consistent with the implicated role of virus-induced necroptosis in restricting infection, viral pathogenesis is restored in Zbp1−/−, Ripk3−/− and Mlkl−/− mice." (PMID 30050136, 2018). "Interestingly, ZBP1−/− mice exhibited significant weight loss compared to WT mice after challenge at days 2, 3, 4, and 5 post infection." (PMID 40416961, 2025). "In addition to the type-I IFN response during ZBP-1 activation, the NF-κB signaling pathway leading to proinflammatory cytokine production also constitutes a line of defense against pathogenic infections." (PMID 39850894, 2024).